HOTAIR (HOX transcript antisense RNA)
Diseases named in the same sentence as HOTAIR in open-access papers (continued):
Sharing a sentence is not in itself a finding about the gene and the disease.
cancer (continued). "Cancer cell exosomes can also transport HOTAIR (HOX transcript antisense RNA) to endothelial cells, thus increasing VEGFA expression to stimulate angiogenesis, explaining why most cancer-cell-derived exosomes can promote angiogenesis." (PMID 36291860, 2022). "Another example is the HOX Transcript Antisense Intergenic RNA (HOTAIR), highly expressed in several cancers, which recruits histone-modifying complexes to target genes establishing suppressive histone marks." (PMID 34298698, 2021). "The main purpose of this study was to analyze the expression of the paralogous 13 HOX genes, normally involved in embryogenic development and frequently deregulated in human cancers, and of the HOX regulating lncRNA HOTAIR in GEP-NENs." (PMID 34208964, 2021). "Besides, HOTAIR may act as competitive endogenous RNA to bind to several microRNAs and suppress their expressions, which can subsequently upregulate the levels of targeted downstream messenger RNAs, thereby leading to further cancer progression." (PMID 34073224, 2021). "Some cancer-related lncRNAs (e.g., MALAT1, HOTAIR, GAS5, and lincRNA-p21) were found to be enriched in exosomes, suggesting that lncRNAs disseminate cell signals and alter the local cellular microenvironment via EVs." (PMID 33514011, 2021). "In this study we were able to show a specific interaction between HOTAIR and YBX1, and we demonstrated that this interaction mediates at least in part the known effects of HOTAIR on cancer cell biology." (PMID 34266873, 2021). "HOTAIR and MALAT1 were the two lncRNAs of which the expression in liver metastases was always observed to be higher than the adjacent non-cancer tissues." (PMID 34307387, 2021). "In the following sections, we will review and highlight the characteristics and functions of some of the lncRNAs, i.e., HOTAIR, NEAT1, H19, MALAT1, and MEG3, frequently involved in several female-oriented cancers." (PMID 34885213, 2021). "The lncRNAs HOTAIR, MALAT1 and MEG3 were also enriched in EVs derived from cervical-vaginal lavages and significantly upregulated in CC patients compared with cancer-free volunteers." (PMID 34552067, 2021). "MiR-146a-5p has been described as a potential upstream activator of HOTAIR in TNBC cells and their functional interaction is able to promote migration and invasion of cancer cells with a prognostic role in TNBC patients." (PMID 33540611, 2021). "In the cancer stem cell (CSC) subpopulation derived from parental MCF7 cells, HOTAIR elevation is detected and responsible for propelling cell proliferation and migration as well as keeping self-renewal capacity." (PMID 34073224, 2021). "HOTAIR and FAL1 can function as oncogenes, which are directly involved with the occurrence and development of cancers." (PMID 33450825, 2021). "Actually, HOTAIR interacted to miR-203, which has been recognized as a pivotal contributor in EMT and cancer stem cell properties through suppressing the expressions of various targets." (PMID 34539782, 2021). "They found that HOTAIR and CCAT1-L were increased in the tissues and cell lines of this cancer, and treatment of HT-29 and HCT-116 cells with DIM decreased these two lncRNAs." (PMID 33805687, 2021). "A multitude of lncRNAs, such as HOTAIR, H19, MALAT1, MEG3, LET and PVT1, are correlated with cancer development." (PMID 34552067, 2021). "Various lncRNAs, such as MALAT-1, ATB, and HOTAIR, mediate the EMT of cancer cells through various mechanisms." (PMID 33664479, 2021). "The other major pathways identified in terms of regulated gene numbers were HOX antisense intergenic RNA) regulatory pathway (HOTAIR) and HLA-F adjacent transcript 10, also known as UBD) cancer signaling pathway (FAT10)." (PMID 34946170, 2021).
cancer (continued). "For example, a well-characterized lncRNA, HOTAIR (HOX Transcript Antisense RNA), has been recognized as a prognostic marker of several cancer types 20-22." (PMID 34512145, 2021). "As PTEN is an upstream regulator of PI3K/AKT signaling which plays major roles in glucose metabolism, and PTEN, is regulated by HOTAIR in cancer cells, we examined if PTEN expression under LPS-stimulation in macrophage and if this is regulated by HOTAIR." (PMID 33420270, 2021). "HOTAIR can be influenced by miRNA regulation and EMT promotion in carcinogenesis, cancer development, and metastasis suggested by many previous studies." (PMID 32117729, 2020). "The data of these datasets supports proposed interaction of HOTAIR and MET and they are very important to show similar results with HCC in different cancer and cellular contexts." (PMID 32650779, 2020). "The knockdown of HOTAIR leads to miR7 upregulation and reverts EMT and BC cancer stem cells proliferation." (PMID 32397382, 2020). "Additional targets of HOTAIR, identified in HepG2, Bel-7402 and Huh7 cells, include RNA binding motif protein 38 (RBM38), miR-145, and miR-122, promoting cancer phenotypes." (PMID 32429062, 2020). "In a variety of cancer cell types, hypoxia induces expression of lncRNAs MALAT1, ZEB2-AS1 and HOTAIR, which are master regulators of alternative splicing, miRNA sponging, EMT, invasion, migration, cancer staminality and metastatic growth." (PMID 32536347, 2020). "HOTAIR acts as a ceRNA to regulate HER2 expression by sponging miR-331-3p and reprogramming the chromatin state to promote cancer metastasis." (PMID 32283739, 2020). "Our results also demonstrated and suggested that the interaction between HOTAIR and miR‐34a‐5p was involved in EMT process to repress tumorigenesis, cancer growth and metastasis, which have been reported in other studies." (PMID 32248643, 2020). "HOTAIR is abnormally high expressed in LSCC, which promotes the occurrence and development of cancer." (PMID 32848755, 2020). "Several lncRNAs such as HOTAIR or MALAT1 are known to exert an important influence in cancer, but there are many other lncRNAs whose role in cancer remains unexplored." (PMID 33333852, 2020). "ZFAS1, as a novel star lncRNA candidate after HOTAIR and MALAT1, is abnormally expressed in various cancers; however, few ZFAS1-related studies on PAAD have been published." (PMID 32550827, 2020). "HOTAIR gene is located in the HOXC gene cluster on chromosome 12, and plays an important role in the development of malignant cancers." (PMID 32394637, 2020). "HOTAIR is a well-known oncogenic lncRNA that is highly expressed in NSCLC, SCLC, and various other human cancers." (PMID 32117734, 2020). "Another study indicated that ANRIL, HOTAIR and MALAT1 were significantly down-regulated in cancer tissue compared to adjacent normal tissues." (PMID 32947877, 2020). "Overexpression of HOTAIR induces genome-wide re-targeting of PRC2 to several hundred genes, leading to altered histone H3 K27 methylation, cancer progression and malignancy." (PMID 30669611, 2019). "Combined overexpression of CASC9 and HOTAIR in the DUS set discriminated perfectly between normal and cancerous tissues, but detected fewer cancer samples." (PMID 31412811, 2019). "The validation results were highly in great agreement with those in microarray, and the expression tendency of HOTAIR, TINCR, LINC00511, LINC00520, MEG3, and ZNF667-AS1 was also consistent with literature reports in other carcinomas." (PMID 31196171, 2019). "Increasing lncRNAs have been reported to regulate cancer pathways and participate in cancer development, such as the well-characterized MALAT1, H19, HOTAIR and MEG3." (PMID 29849506, 2018). "For example, as a well-known lncRNA, HOTAIR, also located at chromosome 12q13.13, is an antisense transcript of HOXC11 and was an oncogenic lncRNA in many different types of cancer." (PMID 30286788, 2018).
cancer (continued). "The expression levels of numerous lncRNAs are altered in several types of cancer, and several lncRNAs are already used as molecular tools for diagnosis and prognosis of cancer like H19, HULC and HOTAIR." (PMID 29755696, 2018). "It has already been revealed that some lncRNAs, such as HOTAIR, H19 and MALAT1, are potential biomarkers in cancer diagnosis and prognosis." (PMID 29549263, 2018). "In contrast, upon depletion of HOTAIR both the ability of cells to undergo EMT and overall cancer stem cell populations were diminished." (PMID 29732012, 2018). "In addition to HOTAIR, other lncRNAs, such as neuroblastoma associated transcript 1 (NBAT1, also known as CASC14), LINC-PINT (also known as MKLN1-AS1) and MIR31 host gene (MIR31HG) have been shown to interact with PRC2 to influence the epigenetic state of cancer cells." (PMID 29443889, 2018). "It is now important to further characterize the interactions between HOTAIR and MKL1, which would contribute to understand the development of cancer." (PMID 29391067, 2018). "The roles of a small number of lncRNAs such as HOTAIR, H19, and MALAT1 have been depicted in cancers, but little is known about LINC00470." (PMID 29866190, 2018). "Several lncRNAs have been confirmed to play an important role in various types of malignant tumors, including PANDAR, ZFAS1, HOTAIR, TUG1 and so on23–26." (PMID 30111807, 2018). "It is also proved that, HOTAIR expression increase along with STAT3 and ATG12 (key of autophagosome formation) through suppressing cancer suppressing micro RNA miR-454-3p in chondrosarcoma." (PMID 30693021, 2018). "In addition to regulate HOX genes, HOTAIR can contribute to the epigenetic repression of several genes within our genome and its misregulation was shown to contribute the epigenetic alterations of different type of cancer cells promoting tumor growth and metastasis." (PMID 29443889, 2018). "Among them, several lncRNAs represent promising noninvasive cancer biomarkers for detection in patient's body fluids, including PCA3, HOTAIR, HULC, MALAT1, H19, LINC00152, RP11-160H22.5, XLOC_014172, LOC149086, AA174084, and UCA1." (PMID 28634418, 2017). "For example, high HOTAIR expression levels are related to HNC development, and lower levels of EMG3 are related to cancer metastasis." (PMID 27802187, 2017). "Although several other lncRNAs have been reported to promote cancer metastasis, such as the well-characterized MALAT1 and HOTAIR, less evidence exists of lncRNAs acting as inhibitors of this process." (PMID 29078818, 2017). "Some cancer-specific lncRNAs, such as ABCC13, HOTAIR, LINC00472, and FER1L4 have also been reported to act as potential diagnostic and prognostic biomarkers in cancers." (PMID 29029488, 2017). "HOTAIR promotes invasiveness and metastasis by silencing the HOXD genes and others, playing an important role in cancer advancement." (PMID 28587155, 2017). "Considering that HOTAIR oncogenic activity is seen in multiple cancers and MEG3 tumor suppressor activity is also observed across cancers, the simple explanation of differing mechanisms in differing tumors does not seem applicable." (PMID 29113413, 2017). "For example, MALAT1, HOTAIR and NORAD in cancer cells can elicit effective cancer inhibitory effect." (PMID 29220444, 2017). "A recent report demonstrated that HOTAIR’s targets, including EMT-related genes, strongly depend on the type of cancer cell in urothelial cancer." (PMID 28931862, 2017). "In summary, the current meta-analysis provides evidence that four functional polymorphisms of HOTAIR involving rs920778, rs7958904, rs4759314, and rs874945 might contribute to genetic susceptibility to cancer risk in Chinese population, whereas rs1899663 may have no impact." (PMID 28938673, 2017). "HOTAIR, HOX transcript antisense RNA, is capable of reprogramming chromatin organization and promoting cancer cell metastasis." (PMID 29156804, 2017).
cancer (continued). "Deleted DNA regions in CD133+ cell population contain known cancer related factors such as ERBB3 (HER3) and HOTAIR." (PMID 28347289, 2017). "Examples of these include HOTAIR, which interacts with Polycomb-repressive complex 2 and LSD1 to promote cancer invasiveness and, more recently, BALR-2, which is implicated in prednisolone treatment resistance by inhibiting AP-1 activation." (PMID 29113332, 2017). "Therefore, HOTAIR may present a potential therapeutic target against cancers." (PMID 28872613, 2017). "HOTAIR silencing reduced methylation of HOXA1, and enhanced the sensitivity of cancer cells to anticancer drugs in SCLC." (PMID 27713133, 2017). "Consistently, other lncRNAs such as HOTAIR, H19 and UCA1 were also found to predict the shorter OS in cancer patients." (PMID 28410241, 2017). "The promoter of the HOTAIR gene can be bound by interferon regulatory factor-1 (IRF1), which inhibits HOTAIR activity in cancer." (PMID 29469819, 2017). "Among seven validated lncRNAs, there is already a considerable research and data for roles of HOTAIR and MEG3 in various cancer types." (PMID 29138748, 2017). "Several lncRNAs, such as HULC, HOTAIR, HOTTIP, GAS5, and HOST2, have been identified as miRNA targets in various cancers, and these findings provide further understanding of lncRNA regulation during tumorigenesis." (PMID 28492554, 2017). "It has been shown that HOTAIR contributes to chemoresistance through PI3K/AKT/MRP1, wnt/β-catenin pathways or downregualtion of p21 in other carcinomas." (PMID 29228709, 2017). "Moreover, meta-analyses have demonstrated that the aberrant expression of HOTAIR may serve as an indicator that predicts poor prognoses both in cancer overall and in particular types of cancers (e.g., digestive system cancers and oestrogen-dependent malignant tumours)." (PMID 27010768, 2016). "The proposed common pathophysiological basis between cancer and CVDs is strengthened by the role of lncRNAs such as MALAT1, p21, ANRIL, and HOTAIR in the development of cancer as well as in CVDs." (PMID 27144026, 2016). "For example, the lncRNAs LOC100128593 and PGM5-AS1 showed the most pervasive down-regulation in 13 cancer types; several well-characterized lncRNAs such as HOTAIR, H19 and PVT1, also showed dysregulation in at least nine different cancer types." (PMID 27147563, 2016). "Among 848 EZH2-bound lncRNAs in MKN45, the metastatic cell line among the three cell lines examined, we found HOTAIR and MALAT1, which are well documented for their involvement in cancer metastasis." (PMID 26871474, 2016). "Except of these, HOTAIR was additionally reported to have significant influence on the proliferation, metastasis, EMT, and drug resistance in various human cancers." (PMID 26967389, 2016). "Circulating lncRNAs as biomarker for cancer diagnosis have been the subject of extensive research for years, such as POU3F3, HOTAIR, H19, MALAT-1, and so on." (PMID 27888803, 2016). "In CRC, HOTAIR closely correlates with members of the PRC2 complex and ectopic overexpression of HOTAIR promoted invasion of cancer cells in vitro." (PMID 26064090, 2015). "Given this recently identified role of HOTAIR, the finding indicative of the positive interaction between HOTAIR and HER2 is worth to research in other types of cancer cells." (PMID 25859406, 2015). "Another lncRNA of great interest is HOTAIR, a lncRNA that has been described in humans, located near the HOXC gene cluster and abundantly expressed in cancer cells." (PMID 26496443, 2015). "DCGs are enriched in Homeobox genes and HOTAIR is a non-coding RNA derived from a HOX gene and involved in the aberrant gene targeting of PRC2 during cancer progression." (PMID 26029238, 2015). "For instance, transforming growth factor-β1 (TGF-β1) activates the expression of HOTAIR in breast and colon cancer cells, and such an induction is required for acquisition of EMT and cancer stem cell phenotypes." (PMID 25491133, 2014).
cancer (continued). "Several of the detected differentially expressed lncRNAs were well described members of cancer-related pathways, including tumor suppressors and oncogenes (e.g. MEG3, Xist, MALAT1, H19, GAS5, and HOTAIR)." (PMID 25264628, 2014). "In particular, the elevated levels of HOTAIR are highly associated with worse OS in Asian, but not in Caucasian, suggesting that interaction between genetic and environmental factors may contribute to cancer development." (PMID 25303230, 2014). "It is important to specifically disrupt the interaction between HOTAIR and PRC2 in cancer cells upon successful molecular and biochemical resolution of the interaction between HOTAIR and PRC2." (PMID 25491133, 2014). "The HOTAIR (for HOX antisense intergenic RNA) level is increased in primary tumors and regulates cancer progression." (PMID 24069260, 2013). "HOTAIR, located in the mammalian HOXC locus, reprograms chromatin state to promote cancer metastasis by interacting with polycomb repressor complex PRC2, determining PRC2 localization and repression of the HOXD locus." (PMID 23455466, 2013). "As a well-characterized lncRNA, HOTAIR (HOX transcript antisense intergenic RNA) has emerged as a significant epigenetic regulator in cancer and non-malignant disorders, involving positive feedback loops and compensatory harmful regulation mechanisms." (PMID 41567340, 2025). "The observed positive correlation between HOTAIR and SPOCK1 suggests that these genes may function synergistically in cancer progression." (PMID 40001977, 2025). "LncRNAs such as p50-Associated COX-2 Extragenic RNA (PACER), Highly Upregulated in Liver Cancer (HULC), HOTAIR, and MAF transcription factor G antisense RNA 1 (MAFG-AS1) are involved in regulating the expression of COX2 in various cancers, influencing immune suppression within the TME." (PMID 40429961, 2025). "In OSCC, silencing HOTAIR led to decreased binding of EZH2 and H3K27me3 with the E‐cadherin promoter, suggesting that HOTAIR may repress the expression of E‐cadherin by recruiting EZH2 and, thereby, inhibiting cancer cell proliferation and invasion." (PMID 40231344, 2025). "Although more and more studies have shown that HOTAIR has important clinical implications in a variety of tumors, Up to now, the role of HOTAIR in pan-cancer has not been reported." (PMID 38696320, 2024). "According to prior research, the allelic frequencies of the HOTAIR gene (rs12826786, rs1899663, and rs4759314) were not statistically different between BC patients and cancer-free controls and were not likely to develop BC." (PMID 38587571, 2024). "HOTAIR promotes matrix metalloproteinase (MMP‐2 and MMP‐9) activity for cell motility and the capacity to dissolve the basement membrane contributing to the invasion of cancer cells." (PMID 39725668, 2024). "HOTAIR transcription, in turn, promotes EMT and metastasis of cancer cells." (PMID 37308974, 2023). "HOTAIR is a 2.2‐kb-long noncoding RNA located on chromosome 12q13.13, transcribed from the homeobox C gene (HOXC) locus, and has been recognized as a regulator of cancer." (PMID 36924407, 2023). "Moreover, transcriptional control of miR-34a by HOTAIR influenced SOX2 (SRY (sex determining region Y)-Box 2), an essential stemness factor regulating the self-renewal capacity of cancer stem cells." (PMID 37175800, 2023). "Furthermore, several cancer-promoting or tumor-suppressing lncRNAs, such as NEAT1, H19, NRON, LUCAT1, and HOTAIR, can be found not only in malignant cells but also in tumor-specific immune cells." (PMID 36911393, 2023). "Fifth, HOTAIR also affects tumor metastasis by affecting the Wnt/β-catenin, TGF-β, VAGE, and PI3K/AKT/MAPK pathways; the role and importance of these signaling pathways in the metastatic potential of various cancers have been demonstrated." (PMID 36924407, 2023).